SGO2 (shugoshin 2)
Description:
Cooperates with PPP2CA to protect centromeric cohesin from separase-mediated cleavage in oocytes specifically during meiosis I. Has a crucial role in protecting REC8 at centromeres from cleavage by separase. During meiosis, protects centromeric cohesion complexes until metaphase II/anaphase II transition, preventing premature release of meiosis-specific REC8 cohesin complexes from anaphase I centromeres. Is thus essential for an accurate gametogenesis. May act by targeting PPP2CA to centromeres, thus leading to cohesin dephosphorylation (By similarity). Essential for recruiting KIF2C to the inner centromere and for correcting defective kinetochore attachments. Involved in centromeric enrichment of AUKRB in prometaphase.
Synonyms: SGOL2; TRIPIN; FLJ25211
Tractability: PROTAC: ubiquitination databases record sites on it.
Gene: Protein-coding gene on chromosome 2 (200,510,008 to 200,584,096, forward strand). Ensembl gene ENSG00000163535.
Subcellular location: Nucleus; Chromosome, centromere; Chromosome, centromere, kinetochore
Subcellular location (Human Protein Atlas): Nucleoplasm; Nuclear bodies
Pathways (Reactome):
Cell Cycle: Amplification of signal from unattached kinetochores via a MAD2 inhibitory signal; EML4 and NUDC in mitotic spindle formation; Mitotic Prometaphase; Resolution of Sister Chromatid Cohesion; Separation of Sister Chromatids
Signal Transduction: RHO GTPases Activate Formins
Gene Ontology:
Molecular function: protein binding
Biological process: homologous chromosome segregation; meiotic sister chromatid cohesion; mitotic sister chromatid cohesion, centromeric
Cellular component: chromosome, centromeric region; mitotic cohesin complex; nucleoplasm; cytosol; kinetochore; nucleus
Genetic constraint (gnomAD): Loss-of-function variants: 52 observed, 80.16 expected, observed/expected ratio (o/e) 0.65, 90% interval 0.52 to 0.82. The upper end of that interval is the gene's LOEUF score, 0.82, which puts it in group 3 of 6, group 1 being the genes least tolerant of losing a copy. Missense variants: 1,201 observed, 1,320.9 expected, observed/expected ratio (o/e) 0.91, 90% interval 0.87 to 0.95. Synonymous variants: 402 observed, 452.69 expected, observed/expected ratio (o/e) 0.89, 90% interval 0.82 to 0.96.
Homologues: Orthologues: chimpanzee SGO2 (99% identical), macaque SGO2 (94% identical), pig SGO2 (66% identical), dog SGO2 (66% identical), mouse Sgo2a (49% identical), rat Sgo2 (49% identical), mouse Sgo2b (46% identical), tropical clawed frog sgo2p (18% identical), zebrafish sgo2 (11% identical). Paralogues in human: SGO1 (8% identical).
Diseases named in the same sentence as SGO2 in open-access papers:
SGO2 is named in the same sentence as 20 diseases in open-access papers, as found by Europe PMC text mining. Sharing a sentence is not in itself a finding about the gene and the disease. The quoted sentences say what the papers report.
hepatocellular carcinoma (3 papers, 2021 to 2023). A malignant tumor that arises from hepatocytes. "Shugoshin2 (SGO2) may participate in the occurrence and development of tumors by regulating abnormal cell cycle division, but its prognostic value in hepatocellular carcinoma (HCC) remains unclear." (PMID 34200261, 2021).
glioma (2 papers, 2016 to 2021). A benign or malignant brain and spinal cord tumor that arises from glial cells (astrocytes, oligodendrocytes, ependymal cells). "We analyzed the association between SGO2 expression and clinical outcomes from Gene Expression Omnibus (GEO) dataset profiles, The Cancer Genome Atlas (TCGA), and Chinese Glioma Genome Atlas (CGGA)." (PMID 34535705, 2021). "These three independent cohort data analyses suggested that high grade gliomas were correlated with SGO2 overexpression." (PMID 34535705, 2021). "In TCGA dataset, the SGO2 mRNA expression level was significantly higher in the WHO grade IV (n = 152) than in grade III gliomas (n = 130; p = 3.91 × 10–18) and in grade II gliomas (n = 61; p = 1.14 × 10−40)." (PMID 34535705, 2021). "Using BrdU assay, we found that SGO2 knockdown can resulted in decreased the proportion of active cell proliferation compared with siControl glioma cells." (PMID 34535705, 2021). "SGO2 mRNA and protein expression in normal brain tissue and glioma cell lines were investigated via quantitative RT-PCR, Western blot, and IHC staining." (PMID 34535705, 2021). "To explore the effect of SGO2 in glioma tumorigenesis, we used siRNA to knock down SGO2 expression in LN229 and GBM8401 cells." (PMID 34535705, 2021). "In conclusion, this is the first study investigating the relationship between SGO2, which is a conserved centromeric protein, and gliomas." (PMID 34535705, 2021). "Further, we explored the biological role of SGO2 in glioma cell migration, proliferation, apoptosis, and protein–protein interaction." (PMID 34535705, 2021). "Expression of MYCN correlated with that of SGO1/SGO2, except in lower-grade gliomas, and SGO1/SGO2 expression tended to be higher in some MYC-overexpressing cancers." (PMID 27539729, 2016). "Moreover, the SGO2 mRNA expression was grater in WHO grade III gliomas then in grade II gliomas (p = 1.43 × 10–13, p adjusted by Bonferroni method)." (PMID 34535705, 2021). "Also, we found that the SGO2 expression was greater in WHO grade III gliomas then in grade II gliomas (p = 1.12 × 10−4, p adjusted by Bonferroni method)." (PMID 34535705, 2021). "Based on these results and the biological function of SGO2, we believe that SGO2 may have crucial role in glioma cells proliferation." (PMID 34535705, 2021). "Furthermore, SGO2 overexpression in high grade gliomas was confirmed using qRT-PCR, Western blot, and IHC staining." (PMID 34535705, 2021). "Then, the Gene Expression Omnibus (GEO) dataset profiles, The Cancer Genome Atlas (TCGA), Chinese Glioma Genome Atlas (CGGA), RT-PCR, and Western blotting analysis suggested that SGO2 might be a new prognostic biomarker for human gliomas." (PMID 34535705, 2021). "In this study, we hypothesized that SGO2 is overexpressed in patients with high-grade gliomas." (PMID 34535705, 2021). "We further investigated the expression of SGO2 mRNA amount normal brain, WHO grade IV glioma cell lines including LN229, U87MG, GBM8401, and U118MG." (PMID 34535705, 2021). "First, it was difficult to collect a large sample of non-tumor brain tissue and low-grade human gliomas to validate SGO2 expression." (PMID 34535705, 2021). "The result suggested that SGO2 protein overexpression in high-grade gliomas compared with non-tumor brain tissues." (PMID 34535705, 2021). "SGO2 mRNA expression predicted higher grade gliomas than non-tumor brain tissues." (PMID 34535705, 2021).
Infertility (2 papers, 2019 to 2024). "Although SGO2 can also be expressed in mitotic cells, SGO2 deficient mice form aneuploid gametes that result in infertility." (PMID 31214493, 2019).
lung carcinoma (2 papers, 2023 to 2025). "To confirm the role of SGO2 in lung cancer cell proliferation, we employed siRNA targeting SGO2 to transfect A549 and H1299 cells." (PMID 37576392, 2023). "For another, downregulation of SGO2 inhibited proliferation, migration, invasion, and EMT of lung cancer cells, underscoring the oncogenic role of dysregulated SGO2 in promoting cancer development through the stabilization of mitotic centromeric and isolation of sister chromatids." (PMID 37576392, 2023). "To investigate this, we employed siRNA to interfere with SGO2 expression in lung cancer cells." (PMID 37576392, 2023). "Additionally, we utilized small interfering RNA (siRNA) to knock out SGO2 in lung cancer cell lines, confirming its effect on proliferation, migration, invasion, and epithelial-to-mesenchymal transition (EMT)." (PMID 37576392, 2023). "In addition, we utilized Transwell assays to measure lung cancer cell migration and invasion and demonstrated that SGO2 knockdown significantly suppressed cell migration and invasion." (PMID 37576392, 2023). "Moreover, the EdU assay revealed a significant reduction in cell growth, thus underscoring SGO2's contribution to lung cancer cell proliferation." (PMID 37576392, 2023). "In addition, the effects of SGO2 knockdown on lung cancer cell proliferation, migration, invasion, and epithelial-to-mesenchymal transition (EMT) were studied in vitro." (PMID 37576392, 2023). "Furthermore, the knockdown of SGO2 led to a decrease in the proliferation, migration, invasion, and EMT processes of lung cancer cells." (PMID 37576392, 2023).
gastric cancer (1 paper, 2022). A primary or metastatic malignant neoplasm involving the stomach. "Finally, SGO2, TTK, and CENPF were associated with the acquired chemoresistance to cisplatin and fluorouracil combination chemotherapy in gastric cancer." (PMID 36213825, 2022). "The key genes had been validated in GSE14210, and SGO2, TTK, and CENPF have been related with the obtained chemoresistance to cisplatin and fluorouracil mixture chemotherapy in gastric cancer." (PMID 36213825, 2022).
glioblastoma (1 paper, 2021). The most malignant astrocytic tumor (WHO grade IV). "Further studies assessing whether SGO2 has another chromosomal localization during the cell cycle in glioblastoma cells and the relationship between SGO2 and gene expression in glioblastoma are areas of future research." (PMID 34535705, 2021).
lung adenocarcinoma (1 paper, 2023). A carcinoma that arises from the lung and is characterized by the presence of malignant glandular epithelial cells. "In the present study, we have utilized the TCGA and GEO databases to corroborate that elevated levels of SGO2 expression in lung adenocarcinoma are associated with a higher TNM stage and a poorer prognosis." (PMID 37576392, 2023).
Sézary Syndrome (1 paper, 2019). "Our results show significant differential gene expression of STAG3, SGO2, SYCP3, and DMC1 in a cohort of Sézary Syndrome patients when compared to healthy controls." (PMID 31214493, 2019).
cancer (9 papers, 2016 to 2025). A tumor composed of atypical neoplastic, often pleomorphic cells that invade other tissues. "Moreover, SGO2 was confirmed to associate with endogenous cancer by a weighted gene co-expression network analysis." (PMID 34200261, 2021). "Based on STRING analysis, MEIKIN is implicated in chromosome segregation and cell cycle regulation, through interactions with key proteins such as SGO1, SGO2, PLK1, and ESPL1, all of which are known to play critical roles in cancer-associated pathways." (PMID 41463182, 2025). "Based on these findings, we investigated the relationship between MYCN or MYC and SGO1/SGO2 expression levels using The Cancer Genome Atlas (TCGA) pan-cancer gene expression datasets." (PMID 27539729, 2016). "Additionally, we analyzed the expression profile of SGO2 and its protein in both cancerous and normal lung tissues, revealing a significant increase in SGO2 expression within cancer tissues and a stronger staining intensity." (PMID 37576392, 2023). "In addition, one study revealed that SGO2 might be related to the expression of meiosis-specific cancer testis antigens." (PMID 34200261, 2021). "Therefore, we can speculate that SGO2, a coding gene that interacts with other genes and closely contributed to the growth and development of tumors, has a vital role in promoting cancer development." (PMID 34200261, 2021). "The most frequent genes were CKAP2L (Cytoskeleton Associated Protein 2 Like), NCAPH (Non-SMC Condensin I Complex Subunit H), and SGO2 (Shugoshin 2), which were the top differential genes in more than 50% of cancers." (PMID 38396175, 2024).
tumor (8 papers, 2021 to 2023). "MODE and ssGSEA analysis to show that high expression of SGO2 in LUAD was associated with a low level of infiltration of major anti-tumor immune cells, indicating that SGO2 overexpression may hinder anti-tumor immunity and lead to a poorer prognosis." (PMID 37576392, 2023). "Given that tumor cells proliferate rapidly and grow, SGO2 may play an important role in delaying chromosomal separation to promote early metastasis and immune evasion." (PMID 37576392, 2023). "Moreover, this study demonstrates for the first time the tumor-promoting role of SGO2 in HCC using cellular experiments." (PMID 36171884, 2022). "In recent years, some researchers have discovered that SGO2 may be combined with other genes to participate in partial tumor occurrence and development." (PMID 34200261, 2021). "In addition, to assess the relationship between the clinicopathological features and expression level of SGO2, high and low expressions of SGO2 were grouped according to tumor grade, tumor stage and T stage, vascular invasion, and ECOG score (all p < 0.05)." (PMID 34200261, 2021). "Recent studies have revealed that SGO2, an essential protector of meiotic cohesion, may contribute to tumor development by regulating abnormal cell division in the cell cycle." (PMID 34200261, 2021). "Notably, high SGO2 expression may have poorer anti-tumor immunity and may therefore be more suitable for immunotherapy to re-establish immune function, while its high expression with a higher TMB could enable LUAD to benefit from multiple therapies." (PMID 37576392, 2023). "Therefore, our results imply that SGO2, as a regulator of the cell cycle, promotes cell proliferation and may augment the metastatic ability of tumor cells, underscoring its prospective use as a new prognostic biomarker for LUAD." (PMID 37576392, 2023). "Notably, high SGO2 expression may have poorer anti-tumor immunity and may therefore be more suitable for immunotherapy to re-establish immune function." (PMID 37576392, 2023). "Moreover, some researchers have discovered that SGO2 may be combined with other genes to participate in partial tumor occurrences and developments in recent years." (PMID 34200261, 2021). "To further investigate the potential of SGO2 as a prognostic marker for LUAD, we evaluated its expression and distribution in tumor samples via RT-qPCR and IHC." (PMID 37576392, 2023). "Prospectively, the results also showed that the expression level of SGO2 in HCC tissues and nontumor tissues were significantly different, and the SGO2 expressed in tumor samples was considerably higher." (PMID 34200261, 2021). "In our study, we downloaded the mRNA levels of SGO2 in nontumor and tumor samples through the public database TCGA and analyzed the relationships between the expression level of SGO2 and the OS and clinicopathology of HCC patients." (PMID 34200261, 2021). "To validate the expression of ASMP, BUB1, CENPF, MAD2L1, NCAPG, SGO2, and TOP2A genes in tumor samples and adjoining nontumor samples, we measured their relative mRNA expressions using qPCR." (PMID 36072975, 2022).
SGO2 also shares sentences with these, for which no sentence is quoted: adrenocortical carcinoma (2 papers); breast carcinoma (2); aneuploidy (1); Cirrhosis (1); colorectal cancer (1); infection (1); liver cancer (1); ovarian insufficiency (1); premature ovarian failure 1 (1); prostate carcinoma (1).